POSTN (periostin)
Diseases named in the same sentence as POSTN in open-access papers (continued):
Sharing a sentence is not in itself a finding about the gene and the disease.
asthma (continued). "Results from Phase 2 studies showed that treatment with lebrikizumab was associated with improvements in lung function and the rate of asthma exacerbations in patients with uncontrolled asthma, particularly in patients with high periostin levels." (PMID 35846226, 2022). "Sputum periostin levels offer an accurate diagnosis of serious asthma with continuous airflow limitation compared with mild-to-moderate asthma." (PMID 36611844, 2022). "Doxycycline decreased nasal periostin levels (p = 0.084), leading to the less frequent onset of asthma and reduced relapse of nasal polyps." (PMID 36611844, 2022). "In this study, we aimed to characterize stable and exacerbation period serum cytokine and periostin levels of 5 different predefined severe asthma phenotypes with real-life data." (PMID 36326393, 2022). "Exhaled NO, blood eosinophils, serum IgE, and periostin are well-studied and established biomarkers for T2-high asthma endotype." (PMID 35409241, 2022). "Periostin-expressing dendritic cells (DCs) from HDM-challenged wild-type mice kept asthma-like features and IL-13 responses after transferring into periostin null mice." (PMID 36611844, 2022). "Periostin seems to play an important role in lung diseases, as reports on idiopathic pulmonary fibrosis and asthma refer to both its prognostic potential and its mediatory role in disease development." (PMID 36551967, 2022). "POSTN was both suggested to be a biomarker of type 2 immune responses, such as asthma, and to be representing tissue remodeling or fibrosis." (PMID 35335934, 2022). "Eosinophils, IgE, FeNO, and periostin are practical biomarkers for Th2-high asthma, whereas neutrophils are easily used for Th2-low asthma." (PMID 36078171, 2022). "Total serum IgE and the levels of BALF Th2 cytokines/chemokines such as CCL17, CCL22, IL-13, IL-17, and periostin were elevated in the severe asthma mice compared to the saline-treated control." (PMID 35958610, 2022). "Both hydroprednisone therapy and glucocorticoid-induced transcript 1 (GLCCI1) overexpression repressed the airway remodeling in asthma mice model via suppressing IL-13/periostin/TGF-β1 axis." (PMID 36611844, 2022). "Eosinophils, IgE, fractional exhaled nitric oxide, and periostin are practical biomarkers for Th2-high asthma." (PMID 36078171, 2022). "There are reports to suggest that periostin supports adhesion and migration of IL-5-stimulated human eosinophils and Th2 inflammation in asthma." (PMID 36078171, 2022). "Taken together, AEO decreased the POSTN and TGF-β expressions in the asthma provoked by allergens and then cadherin switching was promoted by POSTN/TGF-β with the co-expression factors, snail and vimentin." (PMID 35335934, 2022). "In a study of adult asthmatic patients, EBC levels of periostin were more useful to determine the severity of upper respiratory tract infections, while serum levels were more accurate for the assessment of asthma activity." (PMID 34207327, 2021). "Periostin has been recognised as a biomarker for chronic rhinosinusitis comorbid in patients with severe asthma; thus, we describe the following part regarding the utility of serum periostin for chronic rhinosinusitis (CRS)." (PMID 34439751, 2021). "We have also shown that serum periostin increases with the severity of asthma and AD, indicating that it can be a severity biomarker." (PMID 34439751, 2021). "In fact, periostin has been proven to be involved in the pathogenesis of almost all chronic allergic diseases, including asthma, eosinophilic sinusitis, AD, and allergic conjunctivitis." (PMID 34439751, 2021). "In some cases, however, periostin is one of the causes or drivers of the disease (i.e., IBD or asthma), while in others periostin expression seems to be influenced by a primary infection exacerbating inflammation." (PMID 34512647, 2021).
asthma (continued). "Periostin has been shown to be upregulated in the subepithelial region in asthma, AD, allergic conjunctivitis (AC), eosinophilic esophagitis (EoE) and familial idiopathic pulmonary fibrosis (IPF)." (PMID 34512647, 2021). "At week 52, median percentage changes from baseline in periostin in asthma and CRSwNP patients were −18.93% and −41.08% for dupilumab groups, versus −6.94% and −3.52% for placebo groups (both p < .0001 versus placebo)." (PMID 34037993, 2021). "Periostin is a matrix protein, expressed in fibroblast and epithelial cells, that seems to be an adequate biomarker in asthma because it is involved in the Th2 inflammatory response." (PMID 34207327, 2021). "Plasma eotaxin‐3 and serum periostin were significantly suppressed in asthma and CRSwNP; periostin was also significantly suppressed in EoE patients." (PMID 34037993, 2021). "Asthma subjects were stratified into two subgroups, Th2-high, and Th2-low asthma, based on their expression of a three-gene signature of Type 2 inflammation: POSTN, SERPINB2, and CLCA1." (PMID 34088958, 2021). "Another automated assay, the ARCHITECT Periostin Immunoassay, based on the principle of chemiluminescent immunoassay (CLIA) method, was developed to measure the concentration of periostin in serum and has been used in asthma patients as an anti-IL-13 therapy." (PMID 34439751, 2021). "The analyses carried out revealed that asthmatics with high periostin had better FEV1 levels and a reduction in asthma exacerbations by 60% compared with 5% for patients with low periostin." (PMID 34572281, 2021). "Patients with severe asthma who were not specifically using Xolair had higher plasma periostin concentrations than healthy controls, and using Xolair was shown to reduce periostin levels in patients with severe asthma." (PMID 34439751, 2021). "In those cases when BA and AR were combined, the levels of nasal periostin were significantly higher than in patients with asthma alone (520.19 and 4.71 pg/ml, respectively; p<0.05)." (PMID 34796003, 2021). "In patients with asthma and pulmonary fibrosis, periostin has been localized in the basement membrane of the airway walls." (PMID 34512647, 2021). "In asthma, the efficacy of IL-13 antagonists was largely confined to the cohort presenting the IL-13hi biomarker periostin." (PMID 34512647, 2021). "It has strong links with allergic asthma, with high serum levels of periostin being used as a biomarker of asthma severity." (PMID 35387027, 2021). "SERPINB2 along with chloride channel, calcium-activated, family member 1 (CLCA1) and periostin (POSTN), comprise a gene signature for type 2 high asthma." (PMID 34198546, 2021). "Periostin’s effectiveness as a biomarker was shown to be higher than Eos, FeNO and serum IgE in patients with uncontrolled severe asthma and ICS treatment." (PMID 34658882, 2021). "Serum periostin was significantly higher in asthma and ACO than in COPD, whereas serum YKL-40 was significantly higher in COPD and ACO than in asthma." (PMID 32824775, 2020). "Studies using animal models and patient samples have highlighted an active role of periostin in the pathobiology of various inflammatory diseases, including fibrosis, arthritis, chronic allergic skin inflammation, atherosclerosis and asthma." (PMID 33262757, 2020). "Genes upregulated by T2 cytokines and that have been associated with T2 asthma included the eosinophil chemoattractant CCL26 and POSTN (periostin) which is implicated in extracellular matrix remodeling, both biological processes associated with asthma." (PMID 32560723, 2020). "Mansur demonstrated that FeNO had a stronger correlation with asthma exacerbations than blood eosinophils or periostin." (PMID 32443418, 2020). "This leads us to suppose the existence of a link between periostin–TSLP and the Th2 response as asthma is mainly caused by Th2 inflammation with the predominance of mast cells and eosinophils in airways." (PMID 33203095, 2020).
asthma (continued). "On the other hand, AREG protein level in plasma correlates with the level of periostin, a known marker for Th2 high asthma phenotype, which can predict airway eosinophilia in patients with severe asthma." (PMID 33195308, 2020). "It should be underlined that in our three study groups, only patients with asthma were characterized by a very strong positive correlation between IS periostin and TSLP concentrations both at the protein and mRNA levels (r = 0.96 and r = 0.95, respectively)." (PMID 33203095, 2020). "In all three investigated groups, a strong significant correlation was found for sputum periostin concentration at protein and mRNA expression levels: r = 0.98, p < 0.001 for asthma; r = 0.91, p < 0.001 for COPD; and r = 0.79, p < 0.001 for controls." (PMID 33203095, 2020). "In patients with asthma, serum periostin levels were higher when patients suffered from comorbid CRS." (PMID 32015784, 2020). "In general, the results of the study are consistent with existing data on elevated serum and sputum periostin concentration in asthma and COPD patients compared to healthy controls." (PMID 33203095, 2020). "Compared to both hospitalized nonasthmatics and healthy children, children with asthma had significantly elevated levels of periostin, a pleiotropic cytokine that promotes eosinophil recruitment and tissue remodeling in asthma." (PMID 33036262, 2020). "We have also demonstrated that serum periostin is a sensitive biomarker to detect comorbid CRS with NPs (CRSwNP) in patients with asthma." (PMID 32015784, 2020). "In patients with asthma, both IS concentration and mRNA expression of periostin and TSLP correlated positively with IS eosinophil count." (PMID 33203095, 2020). "The relationships between periostin, TSLP, eosinophils, and IL-4 in asthma point to the links between periostin–TSLP and the Th2 response." (PMID 33203095, 2020). "Periostin is a matricellular protein that plays significant roles in allergic airway diseases, such as asthma and CRS." (PMID 33218117, 2020). "Serum periostin, which is an extracellular matrix protein, is a robust marker of T helper type 2 (Th2) inflammation, particularly in asthma." (PMID 32517742, 2020). "Among T2-high asthma biomarkers sputum and blood eosinophil count, serum IgE, serum periostin levels, and levels of nitric oxide in exhaled breath (FeNO) seem to associate with the severity of asthma and the rate and severity of exacerbations." (PMID 31443563, 2019). "The primary endpoint was the reduction in the rate of asthma exacerbations over 52 weeks in biomarker-high patients (periostin ≥ 50 ng/ml or blood eosinophils ≥ 300 cells/μl." (PMID 31866859, 2019). "Several biomarkers of type 2 inflammation, such as FeNO, serum IgE, blood or sputum eosinophils, and serum periostin distinguish type 2-high and type 2-low asthma phenotypes and also predict the responsiveness to type 2 cytokine-targeted therapy." (PMID 31590215, 2019). "Improvement in FEV1 has been observed in patients with asthma with a high serum periostin levels or detectable sputum IL-13 levels following the administration of MoAbs against IL-13." (PMID 31861989, 2019). "In conclusion, as in CRS, also in asthma, the study of periostin is currently limited to the field of research." (PMID 31731479, 2019). "As for asthma, we discussed the role of fractional exhaled nitric oxide (feNO), the role of periostin, and that of biological mediators measured in exhaled breath condensate (EBC) and exhaled air (volatile organic compounds, VOCs)." (PMID 31731479, 2019). "Sputum eosinophils and serum periostin are biomarkers that have been proposed for defining which children with asthma will respond to anti-IgE, anti-IL-5, or anti-IL-13 asthma treatment." (PMID 31294006, 2019). "Briefly, the combinations of IL-10 and POSTN, CHI3L1 with IL-10 and POSTN, or CHI3L1 with IL-8 and POSTN are proposed as good or very good sets of biomarkers to differentiate between the two types of asthma." (PMID 31143187, 2019).
asthma (continued). "In asthma, Type-2 inflammatory cytokines IL-4 and IL-13 induce upregulation of the POSTN gene responsible for the encoding of periostin." (PMID 30065761, 2018). "Periostin is upregulated by IL-13 in bronchial epithelial cells and lung fibroblasts and deposited widely in the bronchi of subjects with asthma." (PMID 30048528, 2018). "When two biomarkers were combined, the combinations of CHI3L1 + POSTN, IL10 + POSTN, IL-8 + PI3, and SERPINB2 + POSTN were good to discriminate severe from moderate–mild asthma, and of smaller importance was the grouping of IL-8 + POSTN." (PMID 29977241, 2018). "Lebrikizumab initially demonstrated improved FEV1 in uncontrolled asthma, particularly in the high-periostin subgroup." (PMID 30386455, 2018). "The present study showed that serum periostin levels were correlated with airflow limitation and showed a better correlation with airflow limitation in patients with severe asthma and high serum TNC levels." (PMID 30473714, 2018). "Periostin, an extracellular matrix protein and a biomarker of the Th2 immune response in asthma, directly activates eosinophils in vitro." (PMID 30323811, 2018). "Serum periostin levels were significantly higher in patients with mild to moderate asthma (P = 0.01), Th2-high (P = 0.029), high peripheral blood eosinophil counts (≥ 0.14 × 109 cells/L) (P = 0.01), and high FeNO levels (≥ 50 ppb) (P < 0.001)." (PMID 30473714, 2018). "Tralokinumab also did not significantly reduce asthma exacerbation rates or improve lung function in patients with severe uncontrolled asthma, except in a post hoc analysis of subgroups with higher periostin or DPP-4 levels." (PMID 30386455, 2018). "Other known and established biomarkers of Th2 predominant asthma are exaled nitric oxide (FeNO) and serum periostin." (PMID 30310816, 2018). "Prior studies demonstrated that inhaled glucocorticoids affect serum periostin levels in asthma and the current study found that patients on azathioprine were less likely to have an increase in periostin level at time of a flare." (PMID 30308057, 2018). "The same study showed that the level of periostin at 2 years of age was predictive of asthma at age 6 years old." (PMID 30598830, 2018). "Data from the large population-based cohort Swedish GA2LEN show that serum periostin relates to type-2 inflammation and lung function in asthma." (PMID 30498567, 2018). "Recent studies have suggested that periostin modulates Th2-mediated asthma pathogenesis by assisting in the recruitment of inflammatory cells, particularly eosinophils, to the lungs." (PMID 28659663, 2017). "IL-13 induces characteristic changes in mRNA and miRNA expression patterns in airway epithelial cells, and it induced protein periostin that is secreted basally from airway epithelial cells and can be used as a biomarker for Th2 high asthma." (PMID 28057889, 2017). "Allergic airways inflammation in asthma is characterized by an airway epithelial gene signature composed of POSTN,CLCA1, and SERPINB2." (PMID 28701525, 2017). "A persistent disease signature associated with IL-13 (CLCA1, POSTN, SERPINB2) was identified in peripheral airways in treatment-resistant severe asthma." (PMID 28045928, 2017). "In a study of human bronchial epithelial cells from asthma patients, an IL-13-inducible gene signature (POSTN, CLCA1, and SERPINB2) was identified that served as a surrogate marker of type 2 airway inflammation." (PMID 29034234, 2017). "Tralokinumab has been shown to have some positive results in reducing asthma exacerbations in patients with elevated levels of periostin or the dipeptidyl peptidase DPP-4." (PMID 28855973, 2017). "We conclude that there is day-time variation of serum periostin in adults with asthma receiving maintenance ICS and LABA therapy, with higher levels in the morning." (PMID 28194189, 2017).
asthma (continued). "Organizers of the Bronchoscopic Exploratory Research Study of Biomarkers in Corticosteroid-refractory Asthma (BOBCAT) concluded that serum periostin is potentially useful for the selection of agents that target Th2 inflammation." (PMID 29176991, 2017). "In recent years, genetic studies of bronchial epithelial cells have discovered several genes, such as protocadherin 1 (PCDH1), periostin (POSTN), serpin family B member 2 (SERPINB2), and chloride channel accessory 1 (CLCA1), associated with asthma phenotypes." (PMID 28725641, 2017). "Periostin is reported to be the most robust biomarker predicting the effectiveness of lebrikizumab, an anti-IL-13 antibody, for treating asthma." (PMID 28219384, 2017). "The present study shows that production of monomeric periostin would be significantly up-regulated in IPF compared to other periostin-high diseases such as AD, SSc, and asthma." (PMID 28355256, 2017). "Serum concentrations of periostin were assessed (ELISA) at baseline, and the frequency of asthma exacerbations was recorded during a one-year follow-up." (PMID 27965769, 2016). "This study sought to determine the relationship between serum and sputum periostin, airway inflammatory phenotype and asthma control." (PMID 27130294, 2016). "For example, elevated levels of serum periostin, an extracellular matrix protein induced by IL-4 and IL-13 in airway epithelium, identified a subset of asthma patients who responded better to lebrikizumab, an anti-IL-13 monoclonal antibody." (PMID 26993628, 2016). "Serum periostin was measured previously by Genentech using both assay platforms in 195 severe asthma serum samples and on average Elecsys® Periostin values were 2.03 times (+/- 0.01 s.e)." (PMID 27130294, 2016). "Although sputum and serum periostin levels are significantly related to sputum eosinophil proportions, their ability to predict eosinophilic asthma in poorly-controlled asthma appears relatively modest." (PMID 27130294, 2016). "In poorly-controlled asthma, sputum and serum periostin levels are significantly related to sputum eosinophil proportions while their ability to predict the presence of eosinophilic asthma is modest." (PMID 27130294, 2016). "In this well-characterised cohort with poorly-controlled asthma, periostin was detected in 78 % of sputum samples at a 1:2 dilution." (PMID 27130294, 2016). "In this regard, serum periostin has been found to correlate with the increase of eosinophil count in peripheral blood, in the induced sputum and with asthma control in patients with severe and uncontrolled asthma." (PMID 27965769, 2016). "In poorly-controlled asthma treated with inhaled corticosteroids, periostin levels are low in airway secretions, but can be detected." (PMID 27130294, 2016). "In the “Th2-high asthma” phenotype, the hallmarks are increased levels of eosinophils and other markers (such as periostin)." (PMID 27942351, 2016). "It made sense, therefore, to use periostin levels as a biomarker for anti–IL-13 therapy particularly because some patients with uncontrolled asthma continue to have increased levels of IL-13 in the sputum, despite the use of systemic corticosteroids and ICSs." (PMID 26334389, 2016). "Having the ability to bind fibronectin, tenascin-C, collagen I, III and V, periostin is involved in the process of subepithelial fibrosis in asthma patients." (PMID 26430389, 2015). "In asthma patients, gene expression of periostin in sputum cells and elevated serum levels of periostin were detected by PCR and ELISA, respectively." (PMID 25981515, 2015). "It is possible that periostin can further lead to a malignant role for asthma since periostin can enhance the production of IL-1." (PMID 25981515, 2015). "More recently, however, a greater role for periostin has been identified in relation to fibroblasts and airway epithelial cells in models of asthma, while fewer studies have addressed the relationship between periostin and other inflammatory cells." (PMID 25981515, 2015).